RRAS2 (RAS related 2)
Description:
GTP-binding protein with GTPase activity, involved in the regulation of MAPK signaling pathway and thereby controlling multiple cellular processes. Regulates craniofacial development.
Synonyms: TC21; NS12
Tractability: Small molecule: a structure with a bound ligand is known; it has a high-quality binding pocket. Antibody: UniProt places it where antibodies can reach, with high confidence; its Gene Ontology location is reachable by antibodies, with high confidence. PROTAC: ubiquitination databases record sites on it; its protein half-life has been measured.
Target class: Enzyme; Hydrolase
Gene: Protein-coding gene on chromosome 11 (14,277,922 to 14,364,506, reverse strand). Ensembl gene ENSG00000133818.
Subcellular location: Cell membrane; Golgi apparatus membrane
Pathways (Reactome):
Signal Transduction: RND1 GTPase cycle
Gene Ontology:
Molecular function: GTPase activity; protein binding; G protein activity; GTP binding
Biological process: osteoblast differentiation; Ras protein signal transduction; establishment or maintenance of cell polarity; signal transduction
Cellular component: extracellular exosome; focal adhesion; Golgi membrane; membrane; plasma membrane; endoplasmic reticulum
Genetic constraint (gnomAD): Loss-of-function variants: 6 observed, 9.49 expected, observed/expected ratio (o/e) 0.63, 90% interval 0.34 to 1.25. That is too few expected variants to judge how well the gene tolerates losing a copy. Missense variants: 119 observed, 143.57 expected, observed/expected ratio (o/e) 0.83, 90% interval 0.71 to 0.96. Synonymous variants: 67 observed, 50.99 expected, observed/expected ratio (o/e) 1.31, 90% interval 1.08 to 1.61.
Gene-disease validity (ClinGen):
ClinGen rates the evidence that RRAS2 causes each of these diseases.
Noonan syndrome (autosomal dominant): Definitive. Noonan Syndrome (NS) is characterized by short stature, typical facial dysmorphism and congenital heart defects.
Homologues: Orthologues: chimpanzee RRAS2 (100% identical), dog RRAS2 (100% identical), macaque RRAS2 (100% identical), mouse Rras2 (100% identical), rat Rras2 (100% identical), zebrafish rras2 (95% identical), tropical clawed frog rras2 (93% identical), guinea pig RRAS2 (82% identical), rabbit RRAS2 (80% identical). Paralogues in human: RRAS (66% identical), MRAS (57% identical), KRAS (52% identical), HRAS (52% identical), NRAS (50% identical), RIT1 (50% identical), RAP1A (48% identical), RAP1B (48% identical), RIT2 (48% identical), RALA (47% identical), RALB (47% identical), RAP2B (41% identical), and 23 more.
Diseases named in the same sentence as RRAS2 in open-access papers:
RRAS2 is named in the same sentence as 64 diseases in open-access papers, as found by Europe PMC text mining. Sharing a sentence is not in itself a finding about the gene and the disease. The quoted sentences say what the papers report.
Noonan syndrome (11 papers, 2022 to 2026). "In this study, we reported two patients with Noonan syndrome-like clinical features and a recurrent and novel RRAS2 pathogenic variant, p.Gly23Val and p.Gly24Glu, respectively." (PMID 38601074, 2024). "RRAS2 missense mutations, including Q72L, have been also identified in Noonan syndrome, a rare developmental disease frequently associated with the deregulation of RAS signaling elements." (PMID 36476833, 2023). "Consequently, the study identified a novel gene mutation, RRAS2, which is a rare autosomal dominant inheritance mutation in Noonan syndrome." (PMID 39831200, 2024). "Noonan syndrome (NS) is a RASopathy most frequently associated with mutations in HRAS, NRAS, KRAS, and RRAS2." (PMID 41517739, 2026). "No variations of the RRAS2 gene [02250.6:c187C>T(p.Arg63Trp)] have been reported in association with Noonan syndrome." (PMID 39831200, 2024).
breast carcinoma (9 papers, 2010 to 2025). "Why RRAS2 overexpression is especially associated with pregnancy-related breast cancers remains a question." (PMID 38987766, 2024). "Taken together, the data showing SNP C allele enrichment, higher RRAS2 expression for the C allele, and the existence of G > C mutations all point out to RRAS2 as a relevant gene driving breast cancer in humans." (PMID 38987766, 2024). "The forced overexpression of RRAS2 in ductal epithelial cells leads to the development of breast cancer in a causal relationship." (PMID 38987766, 2024). "All these data demonstrate that overexpression of wild-type RRAS2 in mice causes breast cancer in a pregnancy-related manner." (PMID 38987766, 2024). "The second important piece of genetic evidence supporting a cause-effect relationship between RRAS2 overexpression and breast cancer is that we found the gene to be amplified in the blood of approximately 28% of breast cancer patients." (PMID 38987766, 2024). "Our findings demonstrate that TNBC driven by RRAS2 overexpression exhibits a pattern of somatic mutations similar to those observed in human breast cancer, particularly in genes involved in stemness, extracellular matrix interactions, and actin cytoskeleton regulation." (PMID 40221767, 2025). "These genetic data strongly suggest overexpression of RRAS2 is causative of human breast cancer." (PMID 38987766, 2024). "The AHSB cohort contains data on the number of pregnancies, age of diagnosis, and lactation, which could be relevant when considering possible associations between RRAS2 overexpression and breast cancer (BC)." (PMID 38987766, 2024). "The increased prevalence of the alternate C allele at the SNP position in tumor samples, along with frequent RRAS2 gene amplification in both tumors and blood of BC patients, suggests a cause-and-effect relationship between RRAS2 overexpression and breast cancer." (PMID 38987766, 2024). "Accordingly, overexpression of RRAS2 could underlie the development of more than two-thirds of human breast cancers." (PMID 38987766, 2024). "Finally, the increased frequency of a single nucleotide polymorphism in the 3’-untranslated region (UTR) of the RRAS2 mRNA (rs8570), associated with stronger overexpression of RRAS2, in human breast cancer patients compared to the healthy population, strongly links RRAS2 with human BC." (PMID 40221767, 2025). "RRAS2 is overexpressed in ~68% of human breast cancers, with this frequency being even higher in TNBC (75%)." (PMID 40221767, 2025). "In KRAS-transformed breast cancer cells, RRAS2 activates a subset of PI3Kα, promoting PI3K-dependent tumorigenesis." (PMID 39788953, 2025). "In our previous work, we described the generation of breast cancer through overexpression of wild-type RRAS2." (PMID 40221767, 2025). "We have previously shown using human MDA-MB-231 breast cancer cell line that RRAS2 knockdown reduces phosphorylation of proteins in the PI3K/Akt/mTORC1 pathway and that R-RAS2 is necessary to maintain BC cell metabolism and protein translation." (PMID 40221767, 2025). "To explore if R-RAS2 promoted breast cancer cell metastasis in vivo, we carried out experiments of orthotopic inoculation of parental and RRAS2-knockdown CBM-MBC21 breast cancer cells into syngeneic C57BL/6 female mice." (PMID 40221767, 2025). "Indeed, targeted overexpression of human RRAS2 in mammary epithelial cells of genetically engineered mice provokes the development of triple-negative breast cancer in all female breeders, demonstrating a causal relationship between RRAS2 overexpression and postpartum-associated breast cancer." (PMID 38987766, 2024). "Among parous breast cancer patients, those with the highest expression of RRAS2 in their tumors were those diagnosed at an age of 50 or younger." (PMID 38987766, 2024). "Here we show that, in addition to CLL, female mice overexpressing RRAS2 in all tissues develop breast cancer, but only after going through pregnancy." (PMID 38987766, 2024).
breast carcinoma (continued). "Surprisingly, we found that the Rosa26-RRAS2fl/fl x Sox2-Cre female mice, with ubiquitous expression of RRAS2, that developed breast cancer (BC) were only those that had been pregnant (breeders)." (PMID 38987766, 2024). "The RNAseq data was also compared with transcriptomic data deposited in the TCGA human breast cancer database to determine which molecular human breast cancer subset is more similar to the mouse breast cancer RRAS2-overexpression model." (PMID 38987766, 2024). "TGLI1 and STAT3 transcription factors interact to co-regulate target genes, Cep70, UPF3A, and RRas2, to mediate aggressive phenotypes in breast cancer." (PMID 39768178, 2024). "All these data indicate that RRAS2 overexpression is a marker of worse prognosis in human breast cancer." (PMID 38987766, 2024). "In agreement with our findings, Basal-type breast cancers are the ones with the highest expression of RRAS2 in the TCGA metadata." (PMID 38987766, 2024). "This indicates that RRAS2 can initiate the development of breast cancer if moderately overexpressed." (PMID 38987766, 2024). "KCZ+BZA co-treatment reduced protein expression of Cep70, UPF3A, and RRas2, shedding new light on the underlying mechanism of combination treatment in HER2-enriched breast cancer and TNBC." (PMID 39768178, 2024). "A prevailing hypothesis is that RRAS2 overexpression may play a driver role in pregnancy-associated TNBC, while serving a supportive or secondary role in luminal breast cancers." (PMID 40221767, 2025). "In parallel with this cause-effect finding in the mouse model, we observed that wild-type RRAS2 is overexpressed in more than 50% of breast cancer samples, including luminal A, luminal B, HER2-enriched, and TNBC subtypes, with the highest frequency (75%) and expression levels found in TNBC." (PMID 40221767, 2025). "In summary, these results show that more than two-thirds of human breast cancers overexpress RRAS2, and therefore, overexpression of this gene could be behind the development of breast cancer." (PMID 38987766, 2024). "The question arising from the mouse data is whether the overexpression of wild-type RRAS2 contributes to the development of human breast cancer." (PMID 38987766, 2024). "Higher than normal expression of RRAS2 not bearing activating mutations is a key driver in the majority of breast cancers, especially those of the triple-negative type and those linked to pregnancy." (PMID 38987766, 2024). "Such an increase in copy number could be related to overexpression of the wild type RRAS2 gene in breast cancer." (PMID 38987766, 2024). "Unlike somatic mutations in the 3’UTR of the RRAS2 gene described just above, no mutations have been described at a significant rate in the coding sequence of RRAS2 in breast cancer." (PMID 38987766, 2024). "This also suggests RRAS2 overexpression as a driver of human breast cancer." (PMID 38987766, 2024). "To study if RRAS2 overexpression could also be a driver oncogene in the development of human breast cancer, we collected a total of n = 397 human breast cancer samples from two biobanks in Spain (AHSB and FIVO) and analyzed RRAS2 overexpression." (PMID 38987766, 2024). "The human data suggest that overexpression of RRAS2, which does not carry activating mutations in the coding sequence, may be behind the development of breast cancer." (PMID 38987766, 2024). "Besides CLL, breast cancer, and cholangiocarcinoma, considering the numerous human tumors that overexpress this gene, it is very likely that RRAS2 overactivation through dose amplification will be implicated in many other cancers with significant impacts on human health." (PMID 38987766, 2024).
breast carcinoma (continued). "The 15 mouse tumor samples grouped closer to the Triple Negative breast cancers than to any of the others, thus confirming our immunohistochemical data, showing that the breast tumors emerging in mice overexpressing RRAS2 most closely resemble the TNBC subtype." (PMID 38987766, 2024). "In addition to clustering by PCA analysis, we compared the 15 independent murine breast tumors emerging in RRAS2-overexpressing mice with the TCGA human breast cancer dataset by unsupervised clustering using the R package DESeq2 as described in the Methods section." (PMID 38987766, 2024). "In this regard, we have recently shown that overexpression of wild-type RRAS2 drives the formation of both chronic lymphocytic leukemia (CLL) and breast cancer in mice." (PMID 36765602, 2023). "In our analysis of mRNA expression in n = 397 breast cancer samples, we found that 68% overexpress the RRAS2 gene compared to the mean of non-tumoral breast tissue samples, with a mean of 18.6 and a median of 2.1." (PMID 38987766, 2024). "Therefore, to our knowledge, overexpressed wild-type RRAS2 is the clearest driver gene leading to breast cancer without any additional intervention." (PMID 38987766, 2024).
chronic lymphocytic leukemia (7 papers, 2022 to 2025). "Rras2 has been linked to ovarian cancer and chronic lymphocytic leukemia." (PMID 37505851, 2023). "We also demonstrated a driver role for RRAS2 in malignant transformation in chronic lymphocytic leukemia (CLL)." (PMID 38987766, 2024). "Additionally, R-RAS2 constitutively interacts with the B-cell receptor (BCR) in leukemic cells from mice with chronic lymphocytic leukemia (CLL) induced by RRAS2 overexpression." (PMID 40221767, 2025). "In contrast, in another recent publication, we demonstrated that overexpression of wild-type human RRAS2 bearing no mutations causes the development of B-cell chronic lymphocytic leukemia in 100% of mice, thus demonstrating that wild-type RRAS2 is an oncogene driver if overexpressed." (PMID 38067115, 2023).
ovarian carcinoma (6 papers, 2010 to 2023). A malignant neoplasm originating from the surface ovarian epithelium. "Finally, one breakend SV found in all members of HRLS affects RRAS2, a gene associated with both breast and ovarian cancers according to the My Cancer Genome database." (PMID 37627102, 2023). "The last SV detected, 11_14348706_14348707_BND_1, was related to the intronic region of the RRAS2 gene, which has previously been described in breast and ovarian cancers." (PMID 37627102, 2023). "A seven-hub-molecule-signature model (RRAS2, HIST1H2BK, ALB, RPL23A, HIBCH, RPS20, and EIF3E) from those 1198 mtDEPs is established to predict the survival time of ovarian cancer." (PMID 35498135, 2022). "A seven-hub-molecule-signature model (HIBCH, HIST1H2BK, ALB, EIF3E, RPS20, RRAS2, and RPL23A) from a multivariate regression analysis can predict the survival risks of ovarian cancer." (PMID 35498135, 2022).
RASopathies (5 papers, 2019 to 2026). "More recently, work on a rare RASopathy variant in the RRAS2 gene reported dysregulation of the Hippo pathway." (PMID 33855281, 2021). "The affected residues (p.Gly23, p.Thr68, p.Gln71) exhibit high evolutionary conservation across RAS family GTPases associated with RASopathies, including HRAS, NRAS, KRAS, and RRAS2." (PMID 41517739, 2026). "Many of the RASopathy-associated genes are in gene families: RAF (BRAF and RAF1), RAS (HRAS, KRAS, MRAS, NRAS, RIT1, and RRAS2), MAP2K (MAP2K1 and MAP2K2), and SOS (SOS1 and SOS2)." (PMID 40496714, 2025). "All three of these RAS proteins have been identified as mutated in RASopathies, along with non-canonical RAS proteins, RIT1, MRAS, RRAS, RRAS2 and RALA." (PMID 35103797, 2022).
leukemia (3 papers, 2022 to 2023). A malignant (clonal) hematologic disorder, involving hematopoietic stem cells and characterized by the presence of primitive or atypical myeloid or lymphoid cells in the bone marrow and the blood. "We have recently demonstrated a driver role for RRAS2 bearing the activating mutation Q72L, which causes T-cell acute lymphocytic leukemia, a leukemia of immature B-cells, a Harderian gland adenoma, and an ovarian cystadenocarcinoma in 100% of mice, among other malignancies." (PMID 38067115, 2023). "The CC genotype correlated with the highest expression of RRAS2 mRNA, whereas expression in leukemias of the GG phenotype was significantly lower than the ones of the CC genotype." (PMID 35120522, 2022). "In summary, we show that overexpression of the wild type form of a rather neglected oncogene, RRAS2, is behind the development of the most frequent leukemia (CLL) in the western world." (PMID 35120522, 2022). "We found that leukemias from male patients had significantly higher expression of RRAS2 than those from female patients." (PMID 35120522, 2022). "We explain this capacity of wild-type RRAS2 to drive the formation of leukemias by its high guanosine nucleotide intrinsic exchange rate, higher than that of classic RAS proteins." (PMID 35120522, 2022). "Conversely, 65.7% of leukemias from male patients overexpressed 4-fold or more RRAS2 mRNA compared with 55.2% for female patients." (PMID 35120522, 2022). "We suggest here that overexpression of wild-type RRAS2, and not activating mutations in RAS members, is what drives transformation of mature B cells towards CLL, at least in 82% of these leukemias." (PMID 35120522, 2022). "The grouping of leukemias according to MBL, CLL, IGHV-UM and IGHV-M showed that RRAS2 expression correlated with CLL, regardless of IgHV status." (PMID 35120522, 2022).
lung carcinoma (3 papers, 2015 to 2022). "The titer of autoantibodies against MFGE8, NRAS, PTP4A1, RRAS2 was measured in serum of 80 esophagus cancer cases (ECs), 80 hepatocellular carcinoma cases (HCCs), 80 lung cancer cases (LCs), and 80 healthy controls by ELISA." (PMID 33718231, 2021). "Our data show a strong increase in transcript abundance for RRAS2, consistent with reports that RRAS2 drives PI3K-dependent tumorigenesis and contributes to late stage metastasis in certain lung cancers." (PMID 25975820, 2015).
lymphoma (3 papers, 2013 to 2023). A malignant (clonal) proliferation of B- lymphocytes or T- lymphocytes which involves the lymph nodes, bone marrow and/or extranodal sites. "Significantly, both wild type and mutated RRAS2 (also known as TC21) are overexpressed in human carcinomas of the oral cavity, esophagus, stomach, skin and breast, as well as in lymphomas." (PMID 24148564, 2013).
brain tumors (2 papers, 2013 to 2025). "In different brain tumor types, RRAS2 mRNA expression was 2- to 22-fold higher than in normal tissue." (PMID 24148564, 2013). "The RRAS2 gene is overexpressed in many malignancies, including brain tumors and especially GB." (PMID 39940838, 2025).
breast ductal adenocarcinoma (2 papers, 2024 to 2025). A breast carcinoma arising from the ducts. "In our previous study, we found that overexpression of unmutated RRAS2 in mammary gland epithelial cells induces the development of ductal breast carcinomas of the TNBC type in a pregnancy-dependent manner." (PMID 40221767, 2025). "All breeder females developed breast ductal adenocarcinomas and had median survival times close to those of Sox2-Cre+ mice, thus confirming that the effect of RRAS2 overexpression is breast epithelium-intrinsic." (PMID 38987766, 2024). "We demonstrate here that the overexpression of wild type RRAS2 is sufficient to drive the development of breast ductal adenocarcinomas in 100% of female mice undergoing cycles of gestation and lactation." (PMID 38987766, 2024).